VDAC1 (voltage dependent anion channel 1)
Diseases named in the same sentence as VDAC1 in open-access papers (continued):
Sharing a sentence is not in itself a finding about the gene and the disease.
cancer (234 papers, 2010 to 2026). A tumor composed of atypical neoplastic, often pleomorphic cells that invade other tissues. "The association of HK with VDAC1 offers several advantages to cancer cells, such as direct access to mitochondrial ATP, thus, coupling cytosolic glycolysis to mitochondrial oxidative phosphorylation." (PMID 40362204, 2025). "In some malignant tumors, VDAC1 overexpression has been found to be associated with important element of the clinical course." (PMID 39449743, 2024). "The effects of VDAC1 depletion were linked to alterations in TFs that regulate signaling pathways associated with cancer hallmarks." (PMID 39456237, 2024). "Although the shift to aerobic glycolysis in gliomas caused by the closure of VDAC1 is less efficient for ATP production, the shift enhances the cancer cells’ resistance to apoptosis." (PMID 36768856, 2023). "VDAC1 is overexpressed in many diseases other than cancer, and its overexpression is associated with cell death induction." (PMID 36900417, 2023). "By association with hexokinase (HK), VDAC1 favors both the production of energy, required by demanding cancer cells, and the protection against cell death, by decreasing the channel conductance for the passage of pro-apoptotic proteins to the cytosol." (PMID 37046443, 2023). "Some VDAC1 pseudogenes have been also found to be expressed in cancer, among them some exclusively or predominantly associated with tumor phenotypes." (PMID 37344914, 2023). "VDAC1 is involved in dysregulated metabolism and cell death, inflammation, and fibrosis associated with cancer and several other diseases." (PMID 36077343, 2022). "In summary, here we showed that depletion of VDAC1 in xenografts of mesothelioma cancer altered the expression of key proteins associated with metabolism, cancer stem cells, differentiation, the TME, and inflammation." (PMID 35883451, 2022). "Due to the small sample size, we were not able to reach a definite conclusion on the association of VDAC1 mutations with prognosis in cancer patients." (PMID 35958281, 2022). "Then, risk scores were calculated for every cancer sample calculated by using the following formula: Riskraw = DAD1*2.316+CYCS*1.426+CSNK2A2*1.576+VPS25*0.728+VDAC1*0.976+TMLHE*0.381+CYTH3*0.024+PRKCA*0.260-TP73*0.567+FZD6*0.047+SQSTM1*0.094-MAP2K7*3.070." (PMID 35185897, 2022). "A central role in oncogenic behavior was ascribed to mitochondrial Ca2+ remodeling, and specifically, the VDAC1-mediated association between the ER and mitochondria was suggested to be essential for cancer cell viability." (PMID 33477936, 2021). "High expression of VDAC1 has been associated with unfavorable outcomes in cancers from lung, head and neck, breast, and liver." (PMID 34658929, 2021). "This suggests that metformin’s multiple effects also involve HK and VDAC1, which are both shown to be associated with cancer and neurodegenerative diseases." (PMID 34671273, 2021). "Detachment of HK from VDAC1 and induction of VDAC1-associated cell death can explain metformin’s anti-cancer effect via the induction of apoptosis." (PMID 34671273, 2021). "The deregulation of apoptosis and metabolism in many cancers have been associated with upregulation of VDAC1." (PMID 33121137, 2020). "Overexpression of VDAC1 in cancer cells is associated with high metastatic potential, low therapeutic efficiency and poor prognosis." (PMID 31678721, 2020). "As a rate-limiting enzyme of glycolysis, HK association with VDAC1 offers several advantages to cancer cells." (PMID 33114780, 2020). "Depleting VDAC1 caused alterations in the transcription factors (TFs) that regulate signaling pathways associated with cancer hallmarks, and modified the expression of over 4000 genes." (PMID 32331482, 2020). "It has been observed that overexpression of VDAC1 in cancer cells is associated with high metastatic potential, low therapeutic efficiency, and poor prognosis." (PMID 32411317, 2020).
cancer (continued). "VDAC1-based peptides–A hallmark of cancer cells is their ability to avoid apoptosis by overexpressing anti-apoptotic proteins such as HK-I, HK-II, Bcl2, and Bcl-xL, which interact with VDAC1 to prevent apoptosis." (PMID 33114780, 2020). "Increasing evidence point out that VDAC1 plays an essential role in mitochondria-mediated apoptosis, which is implicated in neurodegenerative disorders as well as in cancer." (PMID 33336032, 2020). "Depletion of VDAC1 altered the expression of hundreds of genes including transcription factors (TFs) that regulate signaling pathways associated with cancer." (PMID 33114780, 2020). "These VDAC1 depletion-mediated effects involved alterations in transcription factors regulating signaling pathways associated with cancer hallmarks." (PMID 32331482, 2020). "VDAC1, and more specifically VDAC1-ΔC, is therefore at the center of the regulation and control of the Warburg effect, the most prominent hallmark of cancer metabolism." (PMID 33238609, 2020). "CDDP can cause cancer cell apoptosis by binding to mtDNA and the voltage-dependent anion channel 1 (VDAC1) of the mitochondrial outer membrane." (PMID 32824929, 2020). "Synthetic peptides based on VDAC1 binding sites were used to inhibit Bcl2, Bcl-xL, and HKII, preventing their association with VDAC1 and thus inhibiting cancer cells’ ability to evade apoptosis." (PMID 31261935, 2019). "Accumulation of this hypoxic VDAC1-ΔC was associated with resistance of several cancer cell lines to apoptosis induced by chemotherapeutic agents due to interaction of VDAC1-ΔC with Bcl-XL and hexokinase II, two anti-apoptotic proteins." (PMID 29596470, 2018). "This VDAC1/HK2 association entails multiple advantages to cancer cells: a) blocks pro-apoptotic signals; b) fuels glycolysis with a continuous flux of mitochondrial ATP; and c) reduces sensitivity to feedback inhibition by HK2 product, glucose-6-phosphate." (PMID 30400835, 2018). "The association of HK with VDAC1 offers numerous benefits to cancer cells: (a) production and access to energy and metabolites; (b) VDAC1-HK complex acts as an anti-apoptotic protein, preventing cytochrome c release and following apoptosis." (PMID 30011966, 2018). "In fact, the involvement of VDAC1 in cancer metabolism, through its association with HK, has been documented." (PMID 28713289, 2017). "Further, mitochondrial permeability transition pore (mPTP) opening was observed in erastin-treated cancer cells, which was evidenced by VDAC-1 and cyclophilin-D (Cyp-D) association, mitochondrial depolarization, and cytochrome C release." (PMID 27171435, 2016). "As a dynamic regulator of metabolism, VDAC1 has been associated with a metabolic phenotype in cancer cells." (PMID 27659305, 2016). "mPTP opening was observed in erastin-treated cancer cells, which was evidenced by VDAC-1 and Cyp-D association, mitochondrial depolarization and cytochrome C release." (PMID 27171435, 2016). "The mRNAs affected by the loss of VDAC1 are involved in cancer and metastasis, but also in fibrosis, neuromuscular disease and finally in the inflammatory response." (PMID 26322231, 2015). "The apoptosis associated molecular signature VAG, which is composed of VDAC1 and some of its interacting genes, represents a promising prognostic biomarker in human cancers." (PMID 25333947, 2014). "We looked to identify a molecular signature consisting of multiple genes including VDAC1 and its interacting genes that are implicated in the pathology of human carcinomas." (PMID 25333947, 2014). "Specifically, HK, Bcl2, Bcl-xL, actin, and tubulin were found to interact with VDAC1 and alter its channel conductance (see VDAC1 Association with Proteins and Cancer)." (PMID 23233904, 2012). "The dual functions of VDAC1 in both metabolism and apoptosis, as mediated by the protein alone and regulated by associated polypeptides, point to VDAC1 as begin a critical target in addressing cancer therapy." (PMID 23233904, 2012).
cancer (continued). "Disruption of HK binding to VDAC1 by mutation in VDAC1 or by addition of VDAC1-based peptides decreased the survival of cancer cells." (PMID 23233904, 2012). "Additionally, elevated VDAC1 expression has also been associated with cancer prognosis, tumor progression, and sensitivity to chemotherapy." (PMID 39456237, 2024). "Additionally, the effects of VDAC1 depletion involve changes in the levels of transcription factors that regulate signaling pathways associated with key cancer hallmarks." (PMID 39456237, 2024). "Furthermore, it is known that altered VDAC1 expression is associated with many diseases, like cancer, neurodegenerative and cardiovascular diseases." (PMID 37344914, 2023). "The glycolytic activity was associated with active immune signatures in different cancers, suggesting VDAC1 may participate in tumor immune-related mechanisms through metabolic regulation." (PMID 35958281, 2022). "In addition, tumors depleted of VDAC1 showed altered microenvironments and inflammation, both associated with cancer progression." (PMID 35883451, 2022). "Overexpression of VDAC1 has been validated to be associated with cancers, but its role involved in BC remains unclear." (PMID 35729567, 2022). "In addition, our results indicated that VDAC1 expression correlated with the immune infiltration of cancer-associated fibroblasts, suggesting the potential impact of VDAC1 in regulating the tumor microenvironment." (PMID 35958281, 2022). "Strikingly, our study revealed that VDAC1-MPC-mitochondrial homeostasis-glycolysis regulation might be the mechanism underlying the different responses between non-carcinoma and PCa cells." (PMID 35972052, 2022). "Here, we focus on the interactions of VDAC1 with proteins associated with cancer." (PMID 28824871, 2017). "Another hallmark of cancer cells is their ability to avoid apoptosis by activating anti-apoptotic mechanisms associated with drug resistance, including overexpression of anti-apoptotic proteins that interacts with VDAC1." (PMID 28824871, 2017). "Due to its key role in regulating cell life and death, studies have associated VDAC1 with cancer." (PMID 27659305, 2016). "In particular, VDAC1 is the major ion transport channel and is implicated in cancer." (PMID 27069917, 2016). "Moreover, there was no significant change in autophagy-associated proteins in these VDAC1 gene-silenced cancer cells." (PMID 26716410, 2016). "It is easy to hypothesize that as VDAC1 regulates metabolism through its association with HK, cancer cells draw a substantial profit from increasing glycolysis." (PMID 27625993, 2016). "Thus, VDAC1 is an excellent target for anti-cancer therapy since thanks to its observed low genetic variability between patients, the chances that tumors will develop resistance to VDAC1-based drugs by acquiring mutations in VDAC1 are low." (PMID 27289382, 2016). "Indeed, mitochondria-associated HKII has been shown to protect cancer cells from entering apoptosis by blocking the interaction of the pro-apoptotic protein Bax with VDAC1." (PMID 26322231, 2015). "VDAC1 is associated with the mitochondrial pathway of apoptosis, interacting with over-expressed anti-apoptotic proteins present in cancer and mediating the actions of some anti-cancer drugs." (PMID 23233904, 2012). "HK II interacts with VDAC1 to enable its localization to the mitochondria for glycolysis, and deficiency in sumoylation enhances the binding of HK II to VDAC1 on the outer mitochondrial membrane, thereby promoting glycolysis and facilitating cancer cell proliferation and drug resistance." (PMID 38202657, 2023).
cancer (continued). "However, the prognostic power of VDAC1 and its associated genes in human cancers is largely unknown." (PMID 25333947, 2014). "However, the prognostic power of VDAC1 and its associated genes in human cancers is still largely unknown." (PMID 25333947, 2014). "The crucial role in cell fate determination has long made VDAC1 a promising target in cancer research." (PMID 41657337, 2026). "VDAC1 is overexpressed in cancer, Alzheimer’s disease (AD), T2DM, autoimmune diseases such as lupus, cardiovascular diseases (CVDs), inflammatory bowel diseases (IBDs), non-alcoholic fatty liver disease (NAFLD), COVID-19, and others." (PMID 40430574, 2025). "Etoposide induced overexpression and oligomerization of VDAC1 associated with cell death and increased levels of calpain and AEP, and its cancer cell type‐dependent effect." (PMID 39921338, 2025). "In this study, we demonstrated that resveratrol induces the detachment of HK from VDAC1, which both inhibits cancer-cell metabolism and triggers apoptosis." (PMID 40362204, 2025). "To furthermore characterize the response of direct binding to VDAC1/PHB/MMP9 in cancer cells, we examined the effects of CRC cells on cell death and cell cycle." (PMID 41179704, 2025). "The transport of mitochondrial metabolites across the outer mitochondrial membrane (OMM) is mediated by voltage-dependent anion channels (VDACs), with VDAC1 being the most prominent isoform, frequently overexpressed in several types of cancer." (PMID 40941984, 2025). "Given that HK binding to VDAC1 provides both metabolic benefits and apoptotic protection, it has become an important target for anti-cancer therapies." (PMID 40362204, 2025). "Targeting VDAC1 and its interactome by the developed peptide has promising potential for cancer treatment." (PMID 41006687, 2025). "Gelsolin and actin interactions with VDAC1 influence mitochondrial function, energy homeostasis, and apoptosis—which are critical in diseases like cancer and neurodegeneration, where VDAC plays a crucial role in regulating cell survival and death." (PMID 41006687, 2025). "In our published study and using si-m/hVDAC1, we found that silencing VDAC1 expression led to significant changes in cancer cell metabolism." (PMID 39456237, 2024). "Given its multifunctional nature and overexpression in many cancers, VDAC1 presents an attractive target for therapeutic intervention." (PMID 39456237, 2024). "The innovative approach of silencing VDAC1 in cancer therapy is informed by a comprehensive understanding of its complex roles in metabolism, energy regulation, mitochondrial function, and cellular mechanisms." (PMID 39456237, 2024). "Depletion of VDAC1 using si-hVDAC1 affects cancer cell metabolism, leading to inhibited cell proliferation in vitro and in vivo." (PMID 39272828, 2024). "Cellular metabolic and energy reprogramming are critical hallmarks of cancer, and VDAC1 plays a significant role in regulating these processes." (PMID 39456237, 2024). "Drugs that favor the opening of mitochondrial porins can initiate the death of cancer cells, where VDAC1 is an important pro-apoptotic factor, either directly or through other pore-formers." (PMID 38540723, 2024). "Our research showed that targeting VDAC1 with si-VDAC1 led to reprogramming of cancer metabolism, which in turn reduced tumor growth and invasiveness, inhibited angiogenesis, eliminated CSCs, and promoted tumor cell differentiation." (PMID 39456237, 2024). "VDAC1 as a mitochondria-gate keeper regulating the flux of metabolites and ions between the mitochondria and the cytoplasm, regulates cancer cell growth." (PMID 39272828, 2024). "Concerning CAV1, EFEMP1, FBLN2, TGFBI, or VDAC1, their actions are highly context-dependent and can vary across different cancer types and stages." (PMID 39201614, 2024). "The developed VDAC1-derived peptides disrupt these interactions in cancer cells, resulting in impaired energy production, altered cell metabolism, and reduced anti-apoptotic proteins." (PMID 39334905, 2024).
cancer (continued). "As previously discussed, VDAC1 is frequently overexpressed in various cancer types, providing docking sites for the overexpressed HK, and thereby facilitating glycolysis." (PMID 39334905, 2024). "As a transporter of metabolites, VDAC1 plays a crucial role in regulating metabolic and energy homeostasis, significantly influencing the metabolic phenotype of cancer cells." (PMID 39456237, 2024). "As detailed in this review, several groups have developed peptides derived from VDAC1’s interaction sites with its partner proteins, demonstrating their potential in targeting cancer and other diseases." (PMID 39334905, 2024). "By thoroughly understanding VDAC1’s diverse roles in metabolism, energy regulation, mitochondrial functions, and other cellular processes, silencing VDAC1 emerges as a novel and strategic approach to combat cancer." (PMID 39456237, 2024). "Several cancer mouse models have been utilized to highlight the critical role of VDAC1 in cancer survival and tumor growth." (PMID 39456237, 2024). "Our findings show that depleting VDAC1 in cancer cells led to metabolic reprogramming, tumor regression, and disruption of tumor–host interactions." (PMID 39456237, 2024). "As a key regulator of metabolic and energy reprogramming, disrupting cancer energy and metabolism homeostasis by targeting VDAC1 offers a potential anti-cancer therapy strategy." (PMID 38607066, 2024). "Since the anti-apoptotic proteins HK-I, HK-II, Bcl-2, and Bcl-xL have been found to be expressed at high levels in many types of cancer, interfering with their interaction with VDAC1 is an appropriate target for inducing apoptosis." (PMID 39334905, 2024). "We demonstrated that the inhibition of VDAC1 expression led to reprogramming cancer cell metabolism, markedly inhibited tumor growth of both NSCLC and SCLC, and eliminated CSCs associated with tumor recurrence and metastasis." (PMID 39272828, 2024). "Our research has demonstrated that silencing VDAC1 expression using specific siRNA in various tumor types leads to a metabolic rewiring of the malignant cancer phenotype." (PMID 39456237, 2024). "In the present study, we demonstrated that mitochondrial ROS production via the complex III electron transport chain and VDAC1 oligomerization play pivotal roles in cysteine deprivation-induced ferroptosis in various cancer cells." (PMID 39521767, 2024). "The results showed that Metformin binds to VDAC1, reducing mitochondrial calcium and ATP levels, which activates autophagy and kills cancer cells." (PMID 39627451, 2024). "Given that VDAC1 plays a central role in cell metabolism, its enhanced expression provides a significant advantage to cancer cells." (PMID 39456237, 2024). "The results for cancer and other diseases underscore RNAi as a powerful tool for modulating VDAC1 expression, which is frequently overexpressed in these conditions." (PMID 39456237, 2024). "After transfection for 144 h, VDAC1 silencing persisted and significantly inhibited the growth of cancer cells." (PMID 38989148, 2024). "HIF-1α has the ability to attach to hexokinase II and VDAC1, giving cancer cells resistance to apoptosis." (PMID 38737905, 2024). "VDAC1 is highly expressed in different tumors, pointing to its significance in high-energy-demanding cancer cells." (PMID 38607066, 2024). "This review focuses on the role of VDAC1 at the crossroads of cellular metabolism and its involvement in various pathways that are crucial in cancer cell survival and progression." (PMID 39456237, 2024). "In various cancer cell lines, VDAC1 expression levels were found to be elevated compared to those in a control fibroblast cell line." (PMID 39456237, 2024). "This is similar to what we found for other cancer types and is in agreement with the importance of VDAC1 function in regulating energy and metabolite production, as high VDAC1 levels support cancer cell activities." (PMID 38607066, 2024).